CALCA (calcitonin related polypeptide alpha)
Diseases named in the same sentence as CALCA in open-access papers (continued):
Sharing a sentence is not in itself a finding about the gene and the disease.
osteoarthritis (2 papers, 2024 to 2025). A noninflammatory degenerative joint disease occurring chiefly in older persons, characterized by degeneration of the articular cartilage, hypertrophy of bone at the margins and changes in the synovial membrane. "Based on the observation that polymorphisms in the CALCA gene are associated with the onset and progression of osteoarthritis, this study was designed to test a functional relevance of both the PCT/CT and αCGRP transcript in a mouse model of ptOA." (PMID 38396204, 2024). "Based on their impact on bone and cartilage turnover in health and disease, a role of CALCA-encoded peptides in degenerative joint disease has long been suggested." (PMID 38396204, 2024). "In conclusion, this study tested the previously reported association of degenerative joint disease with polymorphisms in CALCA, a well-defined gene and subject to tissue-specific, alternative splicing." (PMID 38396204, 2024). "Polymorphisms of the CALCA gene, giving rise to either a procalcitonin/calcitonin (PCT/CT) or a calcitonin gene-related peptide alpha (αCGRP) transcript by alternative splicing, were reported to be associated with the development of osteoarthritis." (PMID 38396204, 2024). "Fourth, it is also crucial to study the role of CALCA-encoded peptides in primary, non-traumatic osteoarthritis, as it represents the most common cause of degenerative joint disease and exhibits important pathophysiological and biomechanical differences from ptOA." (PMID 38396204, 2024).
pancreatic cancer (2 papers, 2021 to 2025). "The result showed that pancreatic cancer expressed low levels of CALCA, while paracancerous tissues expressed high levels." (PMID 41281753, 2025). "In this study, we performed IHC staining for CALCA in human pancreatic cancer and paracancerous tissues." (PMID 41281753, 2025). "There were thirty CpG island sites in the promoter region of CALCA, with a methylation percentage of 4.2% in pancreatic cancer and 0.7% in paracancer tissues determined by BSP." (PMID 34394823, 2021).
pancreatic ductal adenocarcinoma (2 papers, 2021 to 2022). An infiltrating adenocarcinoma that arises from the epithelial cells of the pancreas. "CpG island methylation of CALCA was found in 85.71% (54/63) pancreatic ductal adenocarcinoma tissues." (PMID 34394823, 2021). "Among the pancreatic ductal adenocarcinoma tissues, 39 cases presented complete methylation of CALCA (61.90%), and 15 cases presented partial methylation (23.81%)." (PMID 34394823, 2021). "It was found that the mean percentage of CpG island methylation in the CALCA promoter region in tissues of pancreatic ductal adenocarcinoma (13.14%) was significantly higher than that in paracancer tissues (3.00%, P = 0.0035)." (PMID 34394823, 2021). "Here, we show that methylation of CALCA and CALCB in pancreatic ductal adenocarcinoma was significantly higher than that in paracancer." (PMID 34394823, 2021).
prostate carcinoma (2 papers, 2013 to 2024). A carcinoma that arises from epithelial cells of the prostate gland. "CALCA stimulates growth and motility of prostate cancer cells and also has essential functions in angiogenesis." (PMID 23969837, 2013). "Similarly, the higher expression of CALCRL was positively associated with metastatic potential in prostate cancer patients, whereas none of RAMPs nor CALCA were." (PMID 39266299, 2024).
seminoma (2 papers, 2021 to 2024). A radiosensitive malignant germ cell tumor found in the testis (especially undescended), and extragonadal sites (anterior mediastinum and pineal gland). "We observed a high frequency of MGMT and CALCA methylation in NSGCTs and demonstrated for the first time that CALCA methylation is associated with non-seminoma tumors, refractory disease, and poor clinical outcome in TGCT patients (range, 26–32 years)." (PMID 34068019, 2021).
thyroid cancer (2 papers, 2019 to 2022). "A Venn diagram that comprised 7039 thyroid cancer prognosis-related DEGs and 304 CALCA-related DEGs revealed 179 thyroid cancer prognosis-related genes that were associated with differences in CALCA-related expression." (PMID 35280443, 2022). "The differential expression of calcitonin mRNA CALCA in thyroid cancer tissues and normal tissues and the expression of the associated genes and pathways were assessed based on data obtained from the databases." (PMID 35280443, 2022). "CALCA expression was significantly higher in thyroid cancer tissues." (PMID 35280443, 2022).
viral infection (2 papers, 2017 to 2025). "Interestingly genes RASD1 NEFL, CALCA and PIK3R5 are more involved in cell signalling and proliferation, possibly reflecting the impact of viral infection on cell-cycle." (PMID 28406989, 2017).
acute kidney injury (1 paper, 2024). Sudden and sustained deterioration of the kidney function characterized by decreased glomerular filtration rate, increased serum creatinine or oliguria. "Additionally, there was a noticeable trend of elevated CALCA hypermethylation in the urine of patients with biopsy-confirmed acute tubular necrosis, which suggests a link between acute kidney injury (AKI) and methylation." (PMID 39595187, 2024).
allergic reactions (1 paper, 2020). "Also, CALCA and MAL were reported to be highly expressed in the allergic reactions of MTIs." (PMID 33221769, 2020).
amyloidosis (1 paper, 2025). A disorder characterized by the localized or diffuse accumulation of amyloid protein in various anatomic sites. "All of these amyloidosis types could be clearly confirmed with varying relative highest abundances of TTR (ATTR1-2 to ATTR1-10), IGLL (ALλ1-2 to ALλ1-6), IGKL (ALκ1-1 to ALκ1-2), SAA (AA1-1 to AA1-3), and CALCA (ACal1-1 to ACal1-3)." (PMID 40701201, 2025).
Anxiety (1 paper, 2025). Intense feelings of nervousness, tension, or panic often arise in response to interpersonal stresses. "The meta-analysis confirmed increased expression of four anxiety-related molecular mediators in response to COVID-19 infection: CALCA, TNF, PLAT, and PPARG, with the latter three associated with neurocognitive decline." (PMID 40766923, 2025). "Specifically, SARS-CoV-2 infection appears to upregulate multiple pro-inflammatory cytokines and secreted proteins (e.g., CALCA, TNF, PLAT, PPARG), which are known to promote anxiety phenotypes, while anxiety itself may modulate key regulators of viral pathophysiology." (PMID 40766923, 2025).
astrocytomas (1 paper, 2012). "A recent report has found an increase of promoter hypermethylation in CALCA and CDH1 genes in high-grade astrocytomas, but they did not see any remarkable methylation frequency of other classical tumor suppressor genes, such as p14ARF, RB1, CDKN2B, or APC." (PMID 22389839, 2012).
autism spectrum disorder (1 paper, 2021). A spectrum of developmental disorders that includes autism, and Asperger syndrome. "Also, calcitonin gene-related peptide 1 (alpha-CGRP), a neuropeptide produced from a different CALCA transcript isoform that produces NPCT, plays an important role in social interactions with autism spectrum disorders." (PMID 33834688, 2021).
carcinoids (1 paper, 2022). "Interestingly, some of the peptidergic genes expressed in only minor subpopulations of normal PNECs (e.g. NPW, NPPA, SST, CARTPT) were detected in many carcinoids, whereas the nearly ubiquitous PNEC peptidergic gene CALCA was absent from most carcinoids." (PMID 36469459, 2022).
colorectal adenocarcinoma (1 paper, 2016). The most common type of colorectal carcinoma. "Another study of four candidate genes in colorectal adenocarcinoma cells demonstrated that males had increased methylation of MTHFR, CALCA, and MGMT compared to females." (PMID 27795744, 2016).
complex regional pain syndrome (1 paper, 2019). A chronic pain syndrome characterized by a disproportionate spontaneous or stimulus-induced pain, accompanied by a variably mixed myriad of autonomic and motor disorders including symptoms such as swelling, allodynia, skin blood supply and trophic disturbances. "There is a network centered on GNG7, that may be involved in connectivity/signaling, comprising HTR2A, EDN1, PNOC (involved in pain signaling) and CALCA (involved in Reflex Sympathetic Dystrophy and Complex Regional Pain Syndrome)." (PMID 30755720, 2019).
cryptorchidism (1 paper, 2023). The failure of one or both testes of a male fetus to descend from the abdomen into the scrotum during the late part of pregnancy. "After a period of prolonged increase, CALCA levels undergo marked reduction, as in patients with cryptorchidism." (PMID 37508506, 2023).
embryonal carcinoma (1 paper, 2017). A non-seminomatous malignant germ cell tumor characterized by the presence of large germ cells with abundant cytoplasm resembling epithelial cells, geographic necrosis, high mitotic activity, and pseudoglandular and pseudopapillary structures formation. "A higher frequency of CALCA methylated samples in embryonal carcinomas or yolk sac tumors (p=0.017) was also observed." (PMID 28881587, 2017).
ischemia (1 paper, 2022). A hypoperfusion of the BLOOD through an organ or tissue caused by a PATHOLOGIC CONSTRICTION or obstruction of its BLOOD VESSELS, or an absence of BLOOD CIRCULATION. "On the other side of the spectrum, LR treatment showed a strong upregulation of the transcript of calcitonin gene-related peptide (CALCA), a protein that is secreted from the heart during ischemia or simulated ischemia." (PMID 35686037, 2022).
metastasis (1 paper, 2011). The spread or migration of cancer cells from one part of the body (where they first appeared) to another. "Of note, there was a trend toward an association between methylation of CALCA and DAPK1 and invasion or adhesion and lymph node metastasis, suggesting that aberrant methylation of these genes is associated with oncologic outcomes of NSCLC patients." (PMID 21507233, 2011).
neuroendocrine tumors (1 paper, 2025). "These in vivo results suggest that the combination of Sulfatinib and Kaempferol preserves its therapeutic effectiveness in tumors deficient in CALCA, thereby offering critical preclinical insights for targeting aggressive neuroendocrine tumors characterized by CALCA genetic alterations." (PMID 41281753, 2025).
Obesity (1 paper, 2020). Accumulation of substantial excess body fat. "In addition, the increased serum CALCA levels were extremely related to obesity, which was supported by the present study." (PMID 33224271, 2020).
ovarian disease (1 paper, 2013). "As for the promoter of CALCA, it was also informative for differentiating methylation between the early stages of ovarian disease and the healthy maintenance of control." (PMID 24565108, 2013).
pancreatic adenocarcinoma (1 paper, 2021). "Methylation of CALCA and CALCB is increased in pancreatic adenocarcinoma, and under that condition, p-AKT and p-CREB levels were decreased." (PMID 34394823, 2021).
squamous cell carcinoma (1 paper, 2011). A carcinoma arising from squamous epithelial cells. "Methylation of CALCA, CDH1, DAPK1, and EVX2 was more common in squamous cell carcinomas (SCC) compared to adenocarcinomas (ADC)." (PMID 21507233, 2011).
synucleinopathy (1 paper, 2022). A neurodegenerative disease that is characterized by the abnormal accumulation of aggregates of alpha-synuclein protein in neurons, nerve fibers or glial cells. "Altogether, APP, CLU, CALCA, and SOD1 may contribute to the α-synuclein-associated synucleinopathy, whereas NEDD4 by posttranslational modification protects against the formation of toxic α-synuclein inclusions." (PMID 36523604, 2022).
type 2 diabetes mellitus (1 paper, 2022). A type of diabetes mellitus that is characterized by insulin resistance or desensitization and increased blood glucose levels. "Studies showed that adipose-derived stem cells (ASCs) in patients with type 2 diabetes mellitus (T2DM) caused upregulation of methylation level in promoter region of CALCA target fragment, resulting in a significant reduction in the osteogenic function of stem cells." (PMID 35132349, 2022).
cancer (23 papers, 2008 to 2025). A tumor composed of atypical neoplastic, often pleomorphic cells that invade other tissues. "CALCA encodes a peptide hormone that plays a key role in maintaining serum calcium levels and the regulation of T and B cells in some cancers, which are often methylated in many types of cancer." (PMID 35422890, 2022). "Using integrated database analysis of The Cancer Genome Atlas (TCGA) and Genotype-Tissue Expression (GTEx), we mined pathways wherein CALCA is involved, identified calcitonin-related genes, and analyzed their functions." (PMID 35280443, 2022). "Previous studies have reported that CALCA is a candidate gene for tumor-specific hypermethylation in cancer." (PMID 34017995, 2021). "Two classic, non-cancer examples are calcitonin-related polypeptide-alpha gene (CALCA) and immunoglobulin M (IgM)." (PMID 29268782, 2017). "This may indicate the involvement of CALCA in complex regulatory mechanisms that affect cancer progression." (PMID 38459043, 2024). "CALCA was differentially expressed in stages TA and I samples, and with lower expression in other stages, which may indicate that CALCA is involved in some complex regulatory mechanisms and affects cancer exacerbation." (PMID 38459043, 2024). "The HLM score was constructed based on six genes, AGXT, TRIB2, ELFN2, PCDHB10, CALCA, and CD79A, which have been previously reported to be associated with the tumorigenesis and progression of various cancer types, including CRC, as well as chemotherapy resistance." (PMID 38902737, 2024). "However, our study suggested that CALCA was highly expressed in cancer tissues, which may need to be further verified by relevant experiments." (PMID 35422890, 2022). "In the study of KIRC cancer progression, CALCA and CPB2 were identified as genes that promote the deterioration process, and CALCA showed significant expression in stage TA and I samples, followed by a decrease in expression." (PMID 38459043, 2024). "For example, 90% sensitivity and 86% specificity for cancer detection was determined when methylation levels of the RASSF1 A, EP300 and CALCA genes were used in combination." (PMID 31450846, 2019). "Third, protein interaction networks of unique DEGs of the two voles relabeled that among the severe hypoxia-specific DEGs in L. mandarinus, the most prominent core genes were RLN3, AVP, CALCA, and SOX2, which regulate responses to stress, metabolism, and cancer." (PMID 32256671, 2020). "Moreover, melanoma-infiltrating TRPV1+ nociceptors overexpressing CALCA and Trka - a high-affinity receptor for NGF - may promote cancer-induced pain hypersensivity." (PMID 39906323, 2024). "The remaining four genes (CALCA, CDKN2B, CDO1 and ADAMTS1) have been described to be methylated in other cancer types, but had never been assessed in TGCT." (PMID 28881587, 2017).
infection (16 papers, 2011 to 2025). The state of being infected such as from the introduction of a foreign agent such as serum, vaccine, antigenic substance or organism. "The circulating levels of procalcitonin are rapidly increased due to involvement of infection induced by bacteria, and the organs and tissues start expressing CALCA gene." (PMID 32963524, 2020). "The study also noted specific methylation alterations in the calcitonin-related polypeptide alpha (CALCA) gene promoter in preterm neonates, correlating with infection type, indicating potential roles for such epigenetic profiles in infection-type stratification." (PMID 40868190, 2025).
tumor (16 papers, 2007 to 2025). "The gene CALCA, encoding the calcitonin gene-related peptide that possess tumor suppressive potential, has been documented as being hypermethylated in several malignancies including head and neck cancer." (PMID 39649173, 2024). "In addition, the methylation level of CALCA gene was also found to be significantly associated with tumor stage (217.7 ± 186.7 in patients with histoligical satge ≥ III vs. 125 ± 129 in patients with histological stage < III, P < 0.05)." (PMID 21639921, 2011). "Throughout the study, the combination treatment group consistently demonstrated suppressed tumor growth along with high CALCA expression." (PMID 41281753, 2025). "The findings revealed that CALCA levels were significantly elevated in normal pancreatic tissues compared to tumor tissues." (PMID 41281753, 2025). "We concluded that CALCA acts as a tumor suppressor in pNETs, inhibiting cell proliferation and angiogenesis by downregulating the PI3K/AKT/mTOR signaling pathway." (PMID 41281753, 2025). "The results indicated that the group subjected to the combination treatment following CALCA knockdown displayed an accelerated tumor growth rate when compared to the group receiving only the combination treatment." (PMID 41281753, 2025). "An EdU incorporation assay further demonstrated that tumor cells with elevated CALCA levels exhibited a marked reduction in DNA replication, whereas CALCA knockdown cells displayed enhanced proliferative capacities." (PMID 41281753, 2025). "IHC analysis revealed a notable increase in Ki-67 expression levels within CALCA knockdown tumors, reinforcing the assertion of CALCA's role as a tumor suppressor." (PMID 41281753, 2025). "The results from the CCK-8 assay indicated that, relative to the untreated knockdown cohort, the combination therapy significantly reduced the proliferative capacity of tumor cells resulting from CALCA depletion." (PMID 41281753, 2025). "The combination of the two pharmacological agents effectively inhibited tumor proliferation instigated by CALCA knockdown." (PMID 41281753, 2025). "The current study expands upon this foundation by conducting a series of in vitro phenotyping experiments aimed at elucidating the role of CALCA in pNETs cell lines, specifically with respect to its impact on tumor proliferation and angiogenic processes." (PMID 41281753, 2025). "The comprehensive data derived from these experiments indicate that CALCA serves as a crucial regulatory gene in the context of combination therapy, with its expression levels exhibiting a significant correlation to anti-tumor efficacy." (PMID 41281753, 2025). "IHC staining for Ki-67 and CALCA demonstrated a negative regulatory relationship between CALCA expression and tumor tissue growth." (PMID 41281753, 2025). "An investigation into the interplay between Sulfatinib, Kaempferol, and CALCA, along with key targets of tumor angiogenesis, was also undertaken." (PMID 41281753, 2025). "The wound healing assay illustrated that HUVECs exposed to the CALCA knockdown conditioned medium demonstrated enhanced tumor cell migration, an effect that was subsequently reversed upon treatment with the combination." (PMID 41281753, 2025). "As an example, MSP primers were designed for CALCA, a gene that has been shown to be methylated in both adult and pediatric neoplasms." (PMID 23024594, 2012). "Moreover, CALCA knockdown undermined the tumor-suppressive impact of the combination when compared to the combination-only group." (PMID 41281753, 2025). "Moreover, the overexpression of CALCA significantly inhibited angiogenesis, whereas CALCA knockdown facilitated vascular neogenesis, subsequently accelerating tumor progression." (PMID 41281753, 2025). "Notably, tumors in the CALCA overexpression group exhibited a significant reduction in both weight and volume, indicating a substantial inhibitory effect on tumor progression." (PMID 41281753, 2025).